MTOR (mechanistic target of rapamycin kinase)
Diseases named in the same sentence as MTOR in open-access papers (continued):
Sharing a sentence is not in itself a finding about the gene and the disease.
Obesity (continued). "The alterations of mTOR occur at a developmental stage at which perintallly-undernourished animals do not show yet obesity or glucose intolerance." (PMID 24040371, 2013). "Many of these effects of obesity operate through the PI3K/ATK/mTOR (e.g., insulin) or LkB-AMPK/mTOR (e.g., adiponectin) pathways, such that obesity affects pathways which may, in turn, support FFM retention." (PMID 22257467, 2012). "However in mice, chronic activation of the mTOR/S6K pathway by POMC neuron-specific deletion of TSC1, demonstrate leptin resistance, hyperphagia and obesity, presumably due to an alteration of the hypothalamic neurocircuitry of energy balance." (PMID 22291999, 2012). "In obesity and type 2 diabetes, chronic hyperglycemia disrupts GI neuron activity by suppressing AMP-activated protein kinase (AMPK) and enhancing mammalian target of rapamycin (mTOR) signaling, leading to impaired nitric oxide (NO)-mediated insulin sensitivity." (PMID 40452923, 2025). "Obesity did not significantly affect abundance of phosphorylated or total CaMKII but did increase abundance of phospho-mTOR and phospho-c-met." (PMID 39283528, 2025). "Notably, ablation of mTOR and LKB prevents diet-induced obesity, yet promotes insulin resistance." (PMID 38693320, 2024). "This paradigm of obesity increased pAMPK levels in females, while Obesity prevented the expected reduction of pRPS6 by CR, indicating Obese female mice were not reaping the benefits of suppressed mTOR signaling attributed to CR." (PMID 38166559, 2024). "Moreover, obesity was found to result in PPAR-driven lipid accumulation in NK cells, and the administration of FAs along with PPARα/δ agonists (i.e., mimicking obesity) blocked mTOR-regulated glycolysis." (PMID 37205182, 2023). "Therefore, it is possible that enhancing both mTOR and TRKB signalling could achieve a more robust rescue of obesity in SMS mice." (PMID 37956053, 2023). "According to studies, the FTO gene was related to obesity and certain types of malignancies, including CRC, by altering the impacts of leptin and adiponectin on colorectal carcinogenesis or participating in adipogenesis and tumorigenesis through the mammalian target protein rapamycin (mTOR)." (PMID 37543622, 2023). "Importantly, the sequencing data presented here supported our preexisting hypothesis that obesity may result in activation of SGK1-related pathways, and we demonstrated increased insulin signaling, mineralocorticoid signaling, and mTOR signaling." (PMID 35998035, 2022). "Although acute activation of mTOR is physiologically important to induce protein synthesis and skeletal muscle growth, chronic elevation of mTOR and/or S6K1 phosphorylation may be one of the culprits hindering muscle anabolism in obesity." (PMID 35350688, 2022). "Interestingly, a low-dose combination of rapamycin and resveratrol (<10 μM) prevented hyperinsulinemia and obesity in HFD mice without inhibiting the mTOR pathway." (PMID 36501200, 2022). "Counter intuitively, we observed that obesity was associated primarily with increased predicted sensitivity with GDSC drugs including those targeting DNA replication and MTOR, but not metabolism pathways which indicates that not all CRC pathways were equally affected." (PMID 35560039, 2022). "Previous research has shown that the downregulation of hepatic autophagy in high-fat diet-induced obesity promotes ER stress and IR, whereas RYGB is reported to improve hepatic lipid metabolism through an increase in the LC3-II/LC3-I ratio and the down-regulation of mTOR." (PMID 35203639, 2022). "Moreover, the HFD-induced obesity activated tissue hypoxia, upregulated the expression of HIF-1α, and influenced autophagy by decreasing the p-AMPK/AMPK ratio and increasing the p-mTOR/mTOR ratio in the hippocampus." (PMID 36188454, 2022).
Obesity (continued). "Unfortunately, no publication has investigated polyphenols targeting mTOR participating in the gut–liver–brain axis; for example, can blocking the mTOR pathway affect appetite or inflammation of the brain in the polyphenols-induced anti-obesity model?" (PMID 36501200, 2022). "For example, obesity-induced hyperleptinemia and increases in insulin/IGF-1 levels, as observed in the present study and in other models, can lead to activation of phosphoinositide 3-kinase and mammalian target of rapamycin (mTOR) signaling and promote primary tumor growth." (PMID 30867005, 2019). "Recent studies have shown that levels of mTOR significantly restrains human and murine adipogenesis and activation of energy metabolism, as previously determined in human NAFLD, using different adipose tissues, while their downregulation obesity and lipotoxicity." (PMID 30917489, 2019). "However, while chronic mTOR activation during obesity or aging might be deleterious, like in CRRT, mTOR activation concurrent with decreased energy balance may preserve protein synthesis, while stimulating fat depletion." (PMID 29596307, 2018). "The reason for obesity‐induced impairments in nutrient‐stimulated muscle protein synthesis, but not exercise‐stimulated muscle protein synthesis is not entirely clear, as both stimuli are thought to share a common anabolic signaling pathway (i.e., the ATK/mTOR pathway)." (PMID 30009507, 2018). "Accordingly, drugs that perturb IPMK signaling actions on major metabolic signaling targets, such as Akt, mTOR, and AMPK, may have therapeutic applications for metabolic syndromes (e.g., obesity, type 2 diabetes) and related eating disorders, such as bulimia and anorexia nervosa." (PMID 23050966, 2012). "Total muscle mTOR protein content is also not always reported, and presenting only ratios of phosphorylated: total protein can mask the true levels of phosphorylated mTOR as several studies have reported greater muscle mTOR protein content in individuals with obesity." (PMID 31263701, 2019). "Furthermore, the mTOR downstream regulator, p70S6KB1, was increased by obesity even without GDM." (PMID 26513002, 2016). "Our present study suggests that SRT1720 treatment may promote the ovarian lifespan of HF diet-induced obesity female mice by suppressing the activation of primordial follicles, the follicle maturation and atresia via activating SIRT1 signaling and suppressing mTOR signaling." (PMID 25330910, 2014). "After the establishment of the obesity‐induced NPC model in vitro, we treated NPCs with or without rapamycin (a specific inhibitor of the mTOR pathway)." (PMID 40090836, 2025). "A main effect of obesity on LC3 was found along with reduced LAMP1 in males with no changes in p‐mTOR Ser4228." (PMID 40677154, 2025). "Although heavily investigated, mechanisms regulating global protein synthesis in skeletal muscle (i.e., mTOR signaling and eIF4F complex formation) may not necessarily alone explain impaired protein metabolism that may occur in a more compartmentalized manner in muscle of humans with obesity." (PMID 35350688, 2022). "Male mTOR-KOPlacenta and littermate controls responded equally in HFD-induced obesity (data not shown)." (PMID 34032632, 2021). "Non-corticoid immunosuppressive medications (CNI, mTOR inhibitors, MMF) did not have a significant effect on weight gain and obesity development." (PMID 24098309, 2013). "Without metformin, the absence of SIRT1 and mTOR block function of CLOCK and BMAL1 during obesity." (PMID 34356626, 2021).
colon carcinoma (442 papers, 2010 to 2026). "YKL-40 was observed to be associated with the PI3K/AKT/mTOR pathway, in which aberrant activation plays an important role in the development of early stages of colon cancer." (PMID 37185706, 2023). "C1QBP has also been implicated in Akt/mTOR signaling, which affects the migration capability of colon cancer cells." (PMID 36674861, 2023). "COMP overexpression in colon cancer cell lines was linked with the promotion of cell proliferation by altering the PI3K-Akt-mTOR axis." (PMID 37207219, 2023). "In colon cancer, wasabi induces autophagy by decreasing the phosphorylation of Akt and mTOR and promotes the expression of microtubule-associated protein 1 light chain 3-II and AVO formation." (PMID 37047794, 2023). "In association, the role of the PI3K/Akt/mTOR signaling pathway was evaluated in colon cancer to characterize survival and proliferation of stem cells." (PMID 35795855, 2022). "Overexpression of PPBP affects the PI3K/AKT/mTOR signaling pathway and is associated with poor prognosis for colon cancer." (PMID 36293321, 2022). "In particular, the PI3K/Akt/mTOR signalling pathway has been found to control the proliferation and survival of colon cancer stem cells, and seems to be linked to colon cancer recurrence and metastasis." (PMID 33923883, 2021). "In PT colon cancer cells, a single treatment with butyrate causes a decrease in phospho-Akt and results in an increase in phospho-AMPKα and a decrease in phospho-mTOR levels, inducing cancer-suppressing autophagy and anticancer effects." (PMID 34829834, 2021). "In this study, we examined the effects of the second-generation mTOR inhibitor PP242 in LS174T cell-induced colon cancer xenograft mouse model in order to reveal the underlying mechanism of PP242." (PMID 33067464, 2020). "Activation of the mTOR pathway is known to be associated with oncogenesis in various types of cancers, such as human cervical and colon cancers." (PMID 29515780, 2018). "Mechanistically, DB-mediated anti-colon cancer activities was associated with the downregulation of stem/oncogenic markers, including β-catenin, c-Myc, and mTOR-associated molecules, while there was upregulation in a tumor suppressor, miR-214." (PMID 30257507, 2018). "This variant, which is in linkage disequilibrium with MTOR c.1787-116A>G, was previously reported to be associated with high risk for colon cancer in a sample from United States." (PMID 30487748, 2018). "Additional important findings from our study include the significantly lower activation of the PI3K/AKT/mTOR pathway in rectal tumors compared to left- and right-sided colon tumors, with lower mutation rates of PIK3CA and PTEN in rectal tumors." (PMID 29156800, 2017). "The mammalian target of rapamycin (mTOR) is frequently activated in colon cancers due to mutations in the phosphatidylinositol 3-kinase (PI3K) pathway." (PMID 22401294, 2012). "The activity of various inhibitors of mTOR was tested on colon cancer cells that harbor distinct mutations of the catalytic subunit of PI3K (PI3KCA)." (PMID 22401294, 2012). "In addition, it has been well established that the hyperactivation of mTOR signaling, caused by the deregulation of upstream components, is a very common feature in human colon cancer." (PMID 36555784, 2022). "Thus, the use of mTOR catalytic inhibitors, in association with other chemotherapeutic agents like irinotecan at low doses, is potentially a hope for colon cancer treatment." (PMID 31627299, 2019). "The use of mTOR inhibitors is potentially a hope in colon cancer treatment and the rational for association with other chemotherapeutic agents like irinotecan seems useful, but requires the identification of subgroups of patients that are most likely to respond." (PMID 31627299, 2019).
colon carcinoma (continued). "However, we observed here that ATP-competitive inhibitors of mTOR exhibited anticancer effects on both PI3KCA mutated as well as on PI3KCA wild type colon cancer cells." (PMID 22401294, 2012). "Notably, the results of the present study demonstrated that lncRNA TINCR knockdown exhibited antitumor effects to reduce mTOR gene and protein expression, and this may be associated with autophagy in colon cancer." (PMID 37051356, 2023). "It has been implicated in promoting colon cancer development through activation of the MAPK and PI3K/Akt/mTOR pathways, both of which are also relevant to migraine pathophysiology." (PMID 41454664, 2026). "The previous study demonstrated that digitoxin induces apoptosis and inhibits proliferation and migration of colon cancer cells by reducing phosphorylation of mTOR substrates p70S6K and 4E-BP1." (PMID 41511947, 2026). "The journal retracts the article titled “Polyphyllin I Promotes Autophagic Cell Death and Apoptosis of Colon Cancer Cells via the ROS-Inhibited AKT/mTOR Pathway”, cited above." (PMID 41312664, 2025). "In this work, the susceptibility of the colon cancer CTC-derived cell line CTC-MCC-41 to AKT and mammalian target of rapamycin (mTOR) inhibitors was evaluated." (PMID 40129297, 2025). "For example, a novel anticancer drug, quinazolinone-chalcone derivative, is reported to interfere with the PI3K/AKT/mTOR signaling cascade in colon cancer HCT-116 cells." (PMID 41180483, 2025). "Mammalian target of rapamycin (mTOR) contributes to colon cancer progression, and OSI-027, as an mTOR inhibitor, suppresses tumorigenesis in colon cancer via the c-Myc/FOXO3a/PUMA axis." (PMID 40901678, 2025). "This promoted an investigation into the effects of fisetin on PI3K/AKT/mTOR and apoptosis pathway on colon cancer cell Caco-2, highlighting its significance as a target in CRC treatment." (PMID 41180483, 2025). "A study has shown that RS inhibits the mTOR pathway, which is involved in the proliferation, growth, and metastasis of colon tumor cells, resulting in increased survival of mice in the RS group compared with the control group." (PMID 41249064, 2025). "This study examined the anti-cancer effects of fisetin, emphasizing its effects on the PI3K/AKT/mTOR and apoptosis pathways in human colon cancer Caco-2 cells." (PMID 41180483, 2025). "Other studies have shown that metformin synergistically enhances the cytotoxic effect of imatinib (tyrosine kinase inhibitor) as well as BEZ235 (an experimental dual inhibitor of PI3K and mTOR kinases) in colon cancer cells." (PMID 41373567, 2025). "Aligning with our findings, their study in colon cancer suggests that increased PD‐L1 due to mTOR inhibition leads to immune suppression and resistance to mTOR inhibitors." (PMID 39258533, 2025). "Recent evidence highlights that the PI3K/AKT/mTOR signaling axis is instrumental in the onset and progression of colon cancer, with its inhibition offering potential therapeutic benefits." (PMID 41011246, 2025). "For instance, PUS7 overexpression enhances proliferation, invasion, and resistance to apoptosis via the phosphatidylinositol 3‐kinase (PI3K)/AKT/mechanistic target of rapamycin kinase (mTOR) pathway in colon cancer cells." (PMID 39834094, 2025). "PUS7 also promotes malignant phenotypes in colon cancer by stimulating the PI3K/AKT/mTOR signalling pathway." (PMID 39834094, 2025).
colon carcinoma (continued). "Further, PSD inhibits the AKT/mTOR pathway, leading to the suppression of colon tumour growth and angiogenesis, together with induction of apoptosis." (PMID 38200409, 2024). "Glabridin inhibits cancer cell proliferation by downregulating PI3K, AKT, and mTOR, upregulating Bax, caspase-3, and caspase-9, and reducing Bcl-2, inducing colon cancer cell death through the intrinsic apoptosis pathway." (PMID 39723390, 2024). "Endometrial, breast, and colon cancers often present activation in the mutant-dependent PI3K–Akt–mTOR signaling pathway." (PMID 39394200, 2024). "In the study evaluating Se-allylselenocysteine activity against HT-29 colon cancer cells, the authors observed that a decline in the expression of mTOR was related to an increase in the level of phosphorylated AMPK in the tested cells." (PMID 39063006, 2024). "Research has discovered that in skeletal muscle cells of diabetic nephropathy and colon cancer cells, butyrate can exert an influence on autophagy and is correlated with mammalian-target-of-rapamycin mTOR pathway alterations." (PMID 38349516, 2024). "The mechanism by which BBR inhibits colon cancer involves the regulation of the PI3K/AKT/mTOR pathway and its upstream proteins." (PMID 39201782, 2024). "Downregulates EIF3G can induce autophagy in colon cancer cells through inhibition of the mammalian target of rapamycin (mTOR) signaling pathway." (PMID 39468015, 2024). "Compared to the control group, the expression of PI3K, Akt, mTOR, p70S6K total protein, and phosphorylated proteins was significantly decreased in AA-treated colon cancer cells." (PMID 38610995, 2024). "PPI inhibited the proliferation of colon cancer SW480 cells by regulating AKT/mTOR and ROS signaling." (PMID 38324023, 2024). "Insulin promotes PD-L1 production and transport in colon cancer stem cells via PI3K/Akt/mTOR signalling." (PMID 39075562, 2024). "Yu, etc. found that inhibiting mTOR phosphorylation also cut the expression of Bcl-2 protein in animal colon cancer model experiments in vivo and in vitro." (PMID 38015410, 2024). "For example, PPI treatment induces autophagic cell death via inhibiting AKT/mTOR signaling, thus suppresses viability of colon cancer cells." (PMID 38745316, 2024). "CXCL6 and CXCL12 promoted the metastasis of colon carcinoma by cooperatively activating the PI3K/Akt/mTOR pathway." (PMID 37491836, 2023). "Conversely, adiponectin, which enhances energy expenditure, can mitigate colon cancer related to obesity by inhibiting the mammalian target of the rapamycin (mTOR) pathway." (PMID 37835359, 2023). "Taken together, these results indicate that SIRT1, Wnt/β-catenin pathway and PI3K/AKT/mTOR pathway are critical to propofol mediated inhibition of colon tumor stemness and EMT in vitro." (PMID 37490168, 2023). "The study of HQ in controlling angiogenesis revealed that HQ exerted anti-tumor activity in colon cancer cells via modulation of mTOR and COX-2 signaling, which together reduced VEGF expression to suppress angiogenesis in human CRC cell and tumor xenograft." (PMID 36755950, 2023). "We predicted that GBN can regulate the phosphatidylinositol 3-kinase (PI3K)–protein kinase B (AKT)–mammalian target of the rapamycin pathway (mTOR) pathway to fight colon cancer." (PMID 36644579, 2023). "In colon cancer cells, the mammalian target of rapamycin (mTOR) is always in an active state and is mainly responsible for cell growth, survival, and metabolism." (PMID 36737760, 2023). "Polyphyllin I increases the production of ROS and inhibits the AKT/mTOR pathway, which encourages colon cancer cells to undergo apoptosis and autophagic cell death." (PMID 37050072, 2023). "Knockout of MTA1 increases the sensitivity of colon cancer to mitochondrial bioenergetic metabolism‐targeted drugs, mTOR inhibitors." (PMID 37442756, 2023).